U3 (Small nucleolar RNA U3 )
Synonyms: LOC124902595
Gene: Small nucleolar RNA gene on chromosome 10 (19,598,247 to 19,598,463, forward strand). Ensembl gene ENSG00000200545.
Gene Ontology:
Biological process: RNA processing
Cellular component: nucleolus
Homologues: Orthologues: chimpanzee U3 (98% identical), macaque U3 (93% identical), rabbit U3 (65% identical), rat LOC120102769 (60% identical). Paralogues in human: U3 (79% identical), U3 (77% identical), SNORD3P1 (77% identical), U3 (76% identical), SNORD3E (74% identical), U3 (73% identical), SNORD3D (72% identical), U3 (72% identical), SNORD3G (72% identical), SNORD3H (72% identical), U3 (71% identical), U3 (70% identical), and 10 more.